SEC11B (SEC11 homolog B, signal peptidase complex subunit (pseudogene))
Description:
Putative component of some signal peptidase complex which removes signal peptides from nascent proteins as they are translocated into the lumen of the endoplasmic reticulum.
Synonyms: SPCS4B; formerly SEC11L2
Gene: Processed pseudogene on chromosome 8 (54,522,799 to 54,523,297, reverse strand). Ensembl gene ENSG00000226098.
Subcellular location: Membrane